SERPINB9 (serpin family B member 9)
Diseases named in the same sentence as SERPINB9 in open-access papers (continued):
Sharing a sentence is not in itself a finding about the gene and the disease.
cancer (26 papers, 2007 to 2025). A tumor composed of atypical neoplastic, often pleomorphic cells that invade other tissues. "Thus, overexpression of Serpinb9 in Ifnar1-KO cancer cells reversed their augmented susceptibility to CD8+ T cell–mediated killing." (PMID 31483286, 2019). "Serpinb9 is the key mediator of enhanced susceptibility of Ifnar1-KO cancer cells." (PMID 31483286, 2019). "For example, some cancer cells increase the expression of inhibitors, such as SERPINB9, which protect them from GZMB-induced apoptosis, allowing to survive despite the presence of GZMB-secreting immune cells." (PMID 40766321, 2025). "An additional layer of complexity was unveiled with the notable overexpression of SERPINB9, a previously documented modulator of cancer stem cell pluripotency, in metastatic EC." (PMID 39528470, 2024). "Building on previous research that highlighted the link between cancer stem cells and drug resistance, we examined the role of SERPINB9 in chemoresistance." (PMID 39528470, 2024). "In vivo, the role of SERPINB9 in maintaining cancer stemness was validated by the limiting dilution assay." (PMID 39528470, 2024). "Most importantly, reintroduction of Serpinb9 expression in Ifnar1-KO cancer cells abrogated their enhanced response to IR." (PMID 31483286, 2019). "SERPINB9 mRNA levels correlated with IFN gene expression signatures in a variety of cancers in the TCGA database." (PMID 31483286, 2019). "Previous studies have shown that SERPINB9 directly inhibits granzyme B, a major effector of CD+ 8 T cell cytotoxicity, and leads to resistance to cytolytic T cell killing in cancer cells, making it a plausible candidate." (PMID 31483286, 2019). "Together these results suggest that Serpinb9 is a downstream mediator of type I IFN signaling in cancer cells." (PMID 31483286, 2019). "Collectively, our results reveal what we believe to be a previously unrecognized link between activation of type I IFN signaling in cancer cells and induction of Serpinb9, which protects cancer cells from CD8+ T cell–mediated cytotoxicity after irradiation." (PMID 31483286, 2019). "Even though SERPINB9 was only transiently induced by type I IFN in cancer cells, its expression was more prolonged after IR." (PMID 31483286, 2019). "We confirmed that Serpinb9 RNA was induced in a dose-dependent fashion after exposure to type I IFN in the 4 cancer cell lines studied here." (PMID 31483286, 2019). "SERPINB9 is a human proteinase inhibitor expressed in certain normal cell types and cancer cells of different origin and can protect the cancer cells from granzyme B (GrB)-mediated apoptosis." (PMID 25133526, 2014). "Targeting Serpinb9 within cancer cells may be beneficial for maximizing IR effectiveness in treating patients with cancer." (PMID 38672681, 2024). "They recovered the known immune evasion factors Stat1 and Serpin Family B Member 9 (Serpinb9) and identified the cancer testis antigen ADAM Metallopeptidase Domain 2 (Adam2) as an immune modulator, whose expression is induced by KrasG12D and further elevated by immunotherapy." (PMID 38162677, 2023). "Another meaningful discovery unearthed that type I IFNs could upregulate SERPINB9 in certain cancer cells, thereby blocking GrB-mediated apoptosis and leading to a subsequent insusceptibility to T cell killing after radiotherapy." (PMID 33868318, 2021). "Serpinb9 was critical in enhancing the vulnerability of Ifnar1-KO cancer cells in our study, consistent with its known role as an inhibitor of granzyme B, an important mediator of T and NK cytoxicity, including killing of cancer cells." (PMID 31483286, 2019). "Radiotherapy with or without anti–PD-L1 may result in a better response in tumors with reduced type I IFN signaling in the cancer cell component and may depend on Serpinb9 expression." (PMID 31483286, 2019). "We identified Serpinb9 as a critical component depleted in the Ifnar1-KO cancer cells." (PMID 31483286, 2019).
cancer (continued). "Serpinb9 levels at baseline as well as their upregulation in response to type I IFN or IR may serve as a common mechanism for cancer cells to survive immune attack." (PMID 31483286, 2019). "Blockade of this pathway or targeting Serpinb9 in cancer cells might be used in the context of radiation therapy to maximize benefits from the antitumor immune response." (PMID 31483286, 2019). "Consequently, SERPINB9 might suppress immune responses, facilitating the evasion of cancer cells from immunosurveillance." (PMID 39528470, 2024). "Overexpression of Serpinb9 may suppress cytotoxic T lymphocytes from eliminating cancer cells." (PMID 31771616, 2019). "It transpires that Serpinb9 (serine protease inhibitor) is an essential factor absent in IFNAR1 knock out cancer cells." (PMID 38672681, 2024). "Moreover, these cells had equivalently increased percentages of permeable cells upon coculture with CD8+ T cells, suggesting that abrogation of type I IFN signaling with or without Serpinb9 overexpression in cancer cells does not affect their recognition or permeabilization by CD8+ T cells." (PMID 31483286, 2019). "We did not detect cross-reactivity with SERPINB9 and CAMK2G, two potential candidates with relevance in human cancer." (PMID 30993208, 2019).
infection (8 papers, 2007 to 2025). The state of being infected such as from the introduction of a foreign agent such as serum, vaccine, antigenic substance or organism. "Expression of Serpinb9 is required to prevent the premature apoptosis of CTL generated in response to lymphocytic choriomenigitis virus (LCMV) or Listeria monoctogenes infection." (PMID 25502180, 2014).
SERPINB9 also shares sentences with these, for which no sentence is quoted: blast (2 papers); leukemia (2); prostate carcinoma (2); bladder cancer (1); Cirrhosis (1); colitis (1); colon tumor (1); Conjunctiva (1); embolic stroke (1); hepatitis C (1); influenza (1); Insulin resistance (1); large cell lymphoma (1); male infertility (1); neuroendocrine carcinoma (1); neurological diseases (1); renal cell carcinoma (1); testis cancer (1).